SMIM10L2A (small integral membrane protein 10 like 2A)
Synonyms: LINC00086; NCRNA00086; MGC39606; LED; LINC0086
Tractability: No criterion of Open Targets' tractability assessment is met for any kind of drug.
Gene: Protein-coding gene on chromosome X (135,421,944 to 135,428,075, forward strand). Ensembl gene ENSG00000178947.
Homologues: Orthologues: chimpanzee SMIM10L2B (100% identical), dog SMIM10L2A (97% identical), mouse Smim10l2a (91% identical), zebrafish smim10l3 (51% identical). Paralogues in human: SMIM10L2B (100% identical), SMIM10L3 (76% identical), SMIM10 (71% identical), SMIM10L1 (60% identical).
Diseases named in the same sentence as SMIM10L2A in open-access papers:
SMIM10L2A is named in the same sentence as 7 diseases in open-access papers, as found by Europe PMC text mining. Sharing a sentence is not in itself a finding about the gene and the disease.
SMIM10L2A shares sentences with these, for which no sentence is quoted: tumor (4 papers); Arthritis (1); cancer (1); gastric cancer (1); infection (1); myocardial ischemia (1); preeclampsia (1).